HMGA2 (high mobility group AT-hook 2)
Diseases named in the same sentence as HMGA2 in open-access papers (continued):
Sharing a sentence is not in itself a finding about the gene and the disease.
cancer (continued). "High expression of HMGA2 mRNA is found in various types of cancers, especially those originating from the biliary tract, large intestine (colon), esophagus, pancreas, and salivary gland (the embedded graph)." (PMID 31581665, 2019). "The meta-analysis results suggested that high expression of HMGA2 was associated with shorter OS and DFS in patients with cancers." (PMID 29997523, 2018). "The difference of overall survival in cancer patients with high HMGA2 expression vs low/median expression." (PMID 29997523, 2018). "Due to its high expression in multiple cancer types at advanced stages as well as in metastases, it has been suggested that HMGA2 functions to drive metastatic ability." (PMID 30228296, 2018). "Combined analysis of 25 studies suggested that the overexpression of HMGA2 correlated with poor OS of cancer patients (pooled hazard ratio [HR] = 1.82; 95% confidence interval [CI] = 1.62–2.05; P < 0.001)." (PMID 29416690, 2018). "Clinicopathological features of the enrolled studies with high expressed HMGA2 in patients with cancer." (PMID 29997523, 2018). "Since HMGA2 is an important gene expression modulator in cancer, we proposed that, through regulation of HMGA2, miR-302a-5p/367-3p also indirectly influences RUNX1 protein expression." (PMID 29391048, 2018). "More strikingly, IGF1R and HMGA2 are well documented as attractive targets for anti-cancer treatment." (PMID 29507664, 2018). "In different cancer models, HMGA2 act as an apoptosis inhibitor inducing BCL2 expression and exerting an opposite effect on the Caspase activity." (PMID 29487711, 2018). "We then analyzed the expression of HMGA2 in different cancers in TCGA datasets through UALCAN, which was an interactive web-portal to perform in-depth analyses of TCGA gene expression data." (PMID 29997523, 2018). "HMGA2, as an important regulatory factor for cancer cell metastasis, can directly affect the expression of EMT-related transcription factors, including Snail and Slug during the EMT process." (PMID 29391048, 2018). "High expression levels of HMGA2 are found in various types of cancer, with recent studies highlighting the important role of miRNAs in the regulation of HMGA2 expression." (PMID 28423547, 2017). "In postnatal life, aside from playing a role in stem cell selfrenewal, Hmga2 was shown to play an important role in a variety of malignant tumors." (PMID 28415789, 2017). "Another path known to regulate HMGA2 expression involves the miRNAs belonging to the let-7 family that are frequently downregulated in cancer, usually resulting in HMGA2 overexpression." (PMID 28423547, 2017). "Recently, a new function of HMGA2 as a replication fork chaperone that protects stem and cancer cells from replication fork collapse induced by chemotherapeutic agents was uncovered, suggesting a previously uncharacterized binding at replication forks." (PMID 28814752, 2017). "As an oncoprotein, HMGA2 is frequently upregulated in a variety of cancers, such as breast cancer, ovarian cancer, colorectal cancer and lung cancer." (PMID 28522832, 2017). "Some of the LSA genes have been shown to be overexpressed in advanced cancers and be associated with unfavorable clinical outcomes such as SOX11, PTPRN, PNCK and HMGA2." (PMID 28427185, 2017). "When expressed in adult tissues from in various organs, Hmga2 is always related to cancer development." (PMID 28415789, 2017). "Hmga2 is expressed in a variety of malignant tumors and in undifferentiated cells during embryogenesis." (PMID 29383160, 2017). "In carcinomas, Hmga2 was found only in the nucleus of K14 positive cells, indicating that Hmga2 also translocated from the membrane to the nucleus during carcinoma development." (PMID 28415789, 2017). "HMGA2 expression directly correlates with the level of malignancy and metastasis in different cancers." (PMID 26799419, 2016).
cancer (continued). "IMP3, another homolog of IMP1, has been shown to prevent miRNA-directed High-Mobility Group AT-hook 2 (HMGA2) mRNA decay in cancer and development." (PMID 27655671, 2016). "Considering the involvement of HMGA2 in the pathogenesis of diverse human cancers, we identified HMGA2 as a key factor in this study among the predicted candidate targets." (PMID 27095441, 2016). "Employing single cell analysis, we determined the effect of HMGA2 on the number of telomere signals per nucleus in individual cancer cells." (PMID 26799419, 2016). "The percentage of micronuclei was found to be significantly decreased in the presence of HMGA2 in both cancer cell models." (PMID 26799419, 2016). "The non-histone chromatin binding protein High Mobility Group AT-hook protein 2 (HMGA2) plays important roles in the repair and protection of genomic DNA in embryonic stem cells and cancer cells." (PMID 26799419, 2016). "Next, to further understand the level of HMGA2 gene expression in human cancers, various cancer cell lines were selected from the National Cancer Institute Cancer Genome Anatomy Project gene expression database." (PMID 26893968, 2016). "This demonstrates the feasibility of the new therapeutic strategy in generating catastrophic genomic instability in HMGA2+ cancer cells by overcoming the telomere stabilizing function of HMGA2." (PMID 26799419, 2016). "So, HMGA2 rarely can be detected in normal adult tissues but is usually reactivated in a variety of benign and malignant tumors." (PMID 26818837, 2016). "To further investigate the telomeric role of HMGA2 in cancer cells, we performed 3D interphase telomere analysis to quantify telomere number and aggregate formation." (PMID 26799419, 2016). "Here we show that HMGA2 localizes to mammalian telomeres and enhances telomere stability in cancer cells." (PMID 26799419, 2016). "In summary, we identified novel roles of HMGA2 in maintaining TRF2 occupancy at telomeres and preventing telomere dysfunction-induced genomic instability in HMGA2+ cancer cells." (PMID 26799419, 2016). "In summary, our data demonstrate a unique and novel role of HMGA2 in telomere protection and promoting telomere stability in cancer cells." (PMID 26799419, 2016). "We concluded that HMGA2 can protect against the actions of telomere-targeting chemotherapeutic drugs in cancer cells." (PMID 26799419, 2016). "This identifies HMGA2 as a new therapeutic target for the destabilization of telomeres in HMGA2+ cancer cells." (PMID 26799419, 2016). "It has been reported that HMGA2 can induce and promote several cancer cells EMT by up-regulating Snail expression." (PMID 26818837, 2016). "The mechanisms that lead to unchecked expression of HMGA2 in cancer are still not fully understood, but miRNA-dependent regulation seems to play a role." (PMID 27835588, 2016). "Upon DNA damage, HMGA2 increases cancer cell survival through prolonged phosphorylation of ATR and its downstream target checkpoint kinase 1 (CHK1)." (PMID 26799419, 2016). "Intriguingly, the presence of HMGA2 resulted in a significantly reduced percentage of anaphase bridges in both cancer cell models." (PMID 26799419, 2016). "Despite the evidence provided from genome-wide screens for HMGA2-target genes using transcriptomic microarray platforms, these studies had focused on different cancer cell models." (PMID 25492890, 2015). "A more recent study confirmed that HMGA2 is highly expressed in metastatic lung adenocarcinoma, where it contributes to cancer progression and metastasis by acting as a competing endogenous RNA for let-7 miRNA family." (PMID 25859543, 2015). "Similar to other human cancers, the let-7 family negatively regulates the HMGA2 oncogene in AT/RT as well." (PMID 26064134, 2015). "HMGA2 plays important roles in promoting cancer metastasis by downregulating miR-200b expression and increasing the level of lysyl oxidase (LOX)." (PMID 25868853, 2015).
cancer (continued). "HMGA2 was found to be highly expressed in metastatic lung adenocarcinoma and contributes to cancer progression and metastasis." (PMID 26179909, 2015). "Recent results demonstrate that the enforced expression of RPSAP52 is able to increase the HMGA2 protein level, induces cancer cell proliferation, and promotes cell cycle progression." (PMID 26137461, 2015). "Conversely, downregulation of HMGA2 protein and decreased proliferation rate of cancer cells were observed when RPSAP52 expression was inhibited by antisense oligonucleotides." (PMID 26137461, 2015). "Taken together, HMGA2 seems to confer cancer cells with migratory and invasive properties, which links well with the pro-mesenchymal and pro-invasive activities HMGA2 elicits in mammary epithelial cells." (PMID 25492890, 2015). "In humans, a re-expression of HMGA2 was also found in various malignant tumours such as leukaemia, lymphoma, mammary, pancreas, non-small cell lung, oral squamous cell, and thyroid carcinoma being an indicator of poor prognosis." (PMID 24914948, 2014). "Recently, we showed that HMGA2 plays an important novel role in protecting the integrity and functionality of arrested replication forks in cancer cells." (PMID 24723911, 2014). "Aberrations of the chromosomal region 12q14-15 that affect HMGA2 were frequently found in human cancers." (PMID 25276782, 2014). "Generally, a delicate balance of let-7 and HMGA2 is discussed to be necessary for cells to switch between undifferentiated and differentiated state and also plays a central role in cancer development and progression." (PMID 24914948, 2014). "This is the first report linking the expression of full-length human HMGA2 in mice with the initiation and progression of a particular cancer." (PMID 25014774, 2014). "High Mobility Group A proteins (HMGA1 and HMGA2) are architectural nuclear factors involved in development, cell differentiation, and cancer formation and progression." (PMID 23936116, 2013). "HMGA2 protein is overexpressed in many types of cancer, such as lung cancer, ovarian cancer, breast cancer, oral squamous cell carcinoma, pancreatic cancer and colorectal cancer." (PMID 23599793, 2013). "A previous study showed that HMGA2 was a direct target for let-7 in human cancer cell lines and let-7 regulated HMGA2 expression in OC and predicts disease progression." (PMID 23251297, 2013). "As endogenous let-7 is capable of suppressing the expression of multiple oncogenes including Ras and Hmga2, inhibition of let-7 allows cancer cells becoming aggressive." (PMID 23075324, 2012). "Disrupting the interaction between let-7 and these binding sites reduces let-7-mediated HMGA2 downregulation and consequently enhances anchorage-independent growth of cancer cells." (PMID 23075324, 2012). "Our study revealed molecular regulatory changes induced by HMGA2 silencing in RB cancer cells, offering mechanistic insights into the anticancer potential." (PMID 23077401, 2012). "HMGA2 is a DNA binding protein highly expressed in embryonic stem cells and cancer cells but undetectable in most normal adult tissues." (PMID 21853155, 2011). "Some of the genes identified to be located close to the generated ChIP DNA fragments play an important role in different types of cancer with high HMGA2 expression." (PMID 21533145, 2011). "From our identified loci, IGF2BP1 and RAD51L1 have been implicated in cancer as have HOXB2, 2q35, and HMGA2." (PMID 20195514, 2010). "Hmga2 is highly expressed in embryonic stem cells, young neural stem cells, and many human cancers, and is moderately expressed in various adult tissues including fibroblasts." (PMID 20668695, 2010). "Hmga2 is expressed robustly in undifferentiated proliferating cells, and its expression during embryogenesis and in a variety of benign and malignant tumors has been characterized." (PMID 18430245, 2008).
cancer (continued). "It has been reported that miR-34 targets Notch, HMGA2, and Bcl-2, genes involved in the self-renewal and survival of cancer stem cells." (PMID 18803879, 2008). "miR-34 targets Notch, HMGA2, and Bcl-2, genes involved in the self-renewal and survival of cancer stem cells." (PMID 18803879, 2008). "In contrast, only a few data on the expression of HMGA2 in human malignant tumour originating from epithelial tissue are available." (PMID 14647145, 2003). "A strong correlation between HMGA2 overexpression and the diagnosis of carcinoma was noted (Fisher's exact probability, P<0.0001)." (PMID 14647145, 2003). "In fact, a strong correlation between HMGA2 overexpression and the diagnosis of carcinoma was statistically verified." (PMID 14647145, 2003). "A strong correlation between HMGA2 overexpression and the diagnosis of carcinoma was statistically verified." (PMID 14647145, 2003). "Finally, considering the pivotal role of HMGA2 in malignant tumours, we conducted a prognosis analysis for PSC based on its expression level." (PMID 41469334, 2026). "HMGA2, as a transcription factor, facilitates oncogenesis and malignant progression by coordinating cell cycle dysregulation, compromising DNA repair machinery, and suppressing cancer cell apoptosis." (PMID 40703517, 2025). "Rare germline HMGA2 variants were discovered in children with cancer, though the functional significance of these variants is not yet known." (PMID 40076747, 2025). "HMGA2 in cancer cells can enhance macrophages recruitment both in vitro and in vivo conditions." (PMID 40351420, 2025). "Drug candidates that directly or indirectly target HMGA2 protein may be worth considering in HMGA2-overexpressing cancers." (PMID 40518465, 2025). "HMGA2 expression was generally higher in cancer than in normal tissues." (PMID 40518465, 2025). "However, HMGA2 is often re-expressed in tumors, where it can promote cancer cell proliferation, cell motility, epithelial-mesenchymal transition, acquisition of cancer stem cell properties, and resistance to chemotherapeutic agents." (PMID 40518465, 2025). "Notably, patients of African origin exhibited significantly elevated wild-type HMGA2 expression during cancer progression, while patients of Asian origin showed lower expression levels." (PMID 41516076, 2025). "In addition, accumulating evidence supports a role for HMGA2 in epithelial-mesenchymal transition (EMT) in various cancers including pancreatic, prostate and colorectal cancer, and its function as a modulator of the TGFβ signaling pathway." (PMID 40004107, 2025). "The overexpression of HMGA2 is a characteristic of malignant tumors." (PMID 40703517, 2025). "Moreover, ER stress-associated transcriptional regulators, such as high mobility group AT-hook 2 (HMGA2), can augment the expression of glutamine transporters and metabolic enzymes, thereby reinforcing glutamine addiction in cancer cells." (PMID 41209558, 2025). "The induction of the expression of Let-7d-5p, which targets high mobility group AT-hook 2 (HMGA2), by lipoprotein exposure was shown to modulate cholesterol influx in macrophages and hence regulate pathogenic processes such as those leading to cancer." (PMID 39334706, 2024). "In addition to known regulatory pathways such as the cell cycle, DNA replication, and retinoblastoma genes in cancer, HMGA2 was significantly correlated with ferroptosis." (PMID 38493165, 2024). "However, further research is required to establish the correlation between HMGA2 protein levels in blood and cancer tissues." (PMID 39085703, 2024). "HMGA2 was shown to be over-expressed during cancer progression by affecting a number of biological processes including the differentiation, survival, as well as apoptosis of cancer cells." (PMID 38671227, 2024).
cancer (continued). "The overexpression of HMGA2 was widely reported in malignant tumors." (PMID 38361751, 2024). "Interestingly, our results from KEGG analyses showed that HMGA2 is involved in cancer through miRNA." (PMID 38802807, 2024). "HMGA2 regulates the cancer cell response to a widely used anti-cancer drug, paclitaxel (PTX)." (PMID 38845972, 2024). "Moreover, elevated expression of the HMGA1 gene or its pseudogenes can increase HMGA2 protein levels, contributing to cancer progression." (PMID 39085703, 2024). "Studies have demonstrated the involvement of HMGA2 in cancer stemness across various cancer types." (PMID 39085703, 2024). "Furthermore, HMGA2 physically interacts with human AP Endonuclease 1 (APE1) in cancer cells, stimulating its activity and promoting the removal of AP sites." (PMID 39085703, 2024). "Furthermore, a new class of non-coding RNAs (miRNAs, circular RNAs, and long non-coding RNAs) plays an essential role in the process of HMGA2-induced metastasis and invasion of cancer by accelerating the EMT process." (PMID 38361784, 2024). "Furthermore, clinical studies have revealed a significant correlation between the expression of HMGA2 in tissue samples and the grading and metastasis of cancer, as well as the survival rate of patients with cancer." (PMID 38361784, 2024). "Thus, ferroptotic cell death was evaluated in HMGA2-altered cancer cells using RSL3 and erastin, two widely accepted chemical inducers of ferroptosis." (PMID 38493165, 2024). "In this review, we discuss alterations in the expression of HMGA2 in various types of cancer." (PMID 38361784, 2024). "Additionally, HMGA2 is regarded as a marker of cancer stem cells, and has the capability to initiate the formation of a colony in OSCC." (PMID 37237385, 2023). "Thus, HMGA2 holds promise as a significant biomarker for the early diagnosis and prognostic assessment of cancer." (PMID 38304037, 2023). "HMGA2 mRNA was highly expressed in the three cancer cell lines." (PMID 37445942, 2023). "A growing number of studies have unveiled that HMGA2 is upregulated in varying cancers and mainly uses miRNAs as upstream targets to affect proliferation, migration, and invasion of multiple cancer cells, thus modulating cancer development." (PMID 37529164, 2023). "Research indicates that HMGA2 accelerates cancer progression by activating multiple pathways." (PMID 38304037, 2023). "However, several studies have demonstrated a strong relationship between HMGA2 and cancer chemotherapy resistance, and we cannot completely dismiss this conclusion based on a single study." (PMID 38304037, 2023). "Collectively, the impacts of HMGA2 interactions with specific protein partners on cell survival, genome stability, proliferation, and differentiation programs highlight the clinical relevance of HMGA2 protein interactions in stem cell and cancer biology." (PMID 36835656, 2023). "In pancreatic cancer, the protein Lin28B in cancer cell-derived exosomes is transformed into these neighbor cancer cells to activate the Lin28B/let-7/HMGA2/PDGFB signaling pathway, promoting interaction with PSCs to enhance their migration to micro-metastatic sites." (PMID 37173915, 2023). "Because HMGA2 is expressed and secreted by NPC cells, it is possible that cancer-secreted HMGA2 can be detected in the circulation of NPC patients, where HMGA2 may serve as a prognostic marker for metastatic potential." (PMID 35388172, 2022). "Our findings broaden the understanding of HMGA2 in cancer metastasis." (PMID 35388172, 2022). "Furthermore, our results confirmed that the silencing of HMGA2 in the cancer cells considerably inhibited cell migration." (PMID 35620335, 2022). "It suggests that the effect of HMGA2 differs in different cancers." (PMID 34976223, 2022).